CSMD3 (CUB and Sushi multiple domains 3)
Diseases named in the same sentence as CSMD3 in open-access papers (continued):
Sharing a sentence is not in itself a finding about the gene and the disease.
tumor (54 papers, 2015 to 2025). "We also found increased mutations in CSMD3, a tumor suppressor gene, where mutations have been shown to lead to the enhancement of tumor cell proliferation and metastasis and, consequently, contributing to adverse clinical manifestations." (PMID 39196408, 2024). "In contrast, the RRGS-High subgroup is characterized by mutations in genes such as MUC16, PCLO, and CSMD3, which are commonly associated with more aggressive tumor features and poorer outcomes." (PMID 39668832, 2024). "Indeed, it has been reported that mutations in CSMD3 are strongly associated with increased tumor mutational burden in OC and poor clinical prognosis." (PMID 40697329, 2025). "In addition, we performed the expression profiles of significantly mutated genes in one normal group and two tumor groups; we identified 20 DEGs; among them CSMD3, DCHS2, LRP2, RYR2, and ZFHX4 were significantly negatively correlated with PFS." (PMID 35975176, 2022). "In addition, we performed the expression profiles of significantly mutated genes between the normal group and tumor groups and identified 20 differentially expressed genes (DEGs); among them, CSMD3, DCHS2, LRP2, RYR2, and ZFHX4 were significantly negatively correlated with PFS." (PMID 35975176, 2022). "CSMD3 and MUC16 mutations are highly correlated with increased tumor mutation burden (TMB) and poor clinical prognosis." (PMID 41419193, 2025). "Our study on COAD using tumor mutation burden (TMB) analysis revealed a slightly higher TMB in the high-risk group compared to the low-risk group, particularly in the CSMD3 gene." (PMID 37701039, 2023). "Among these genes, BRCA1, RB1, RBAK and CSMD3 are tumour suppressors, while TRRAP functions as an oncogene." (PMID 35735060, 2022). "Of the four putative tumor suppressors, CSMD3 has a disputed cancer role and a likely inflated mutation rate, while CDKN2B cooperates with its paralog CDKN2A to inhibit cell cycle, supporting its tumor suppressor role." (PMID 35078504, 2022). "Combined analysis of complimentary DNA microarray and microRNA array identified microRNA-873-mediated reduced expression of the CUB and Sushi multiple domains 3 (CSMD3) protein, a putative tumor suppressor, in TgSW172* mice." (PMID 27918551, 2016). "Similarly, mutations in CSMD3, LRP1B, and PCLO are closely associated with tumor development and progression." (PMID 41235252, 2025). "As shown in the waterfall plot, there are variations in the tumor mutational burden (TMB) of two subtypes, and the frequencies of TTN, CSMD3, MUC16, RYR2, LRB1P and ZFHX4 mutations in the high-risk group were considerably higher than those in the low-risk group." (PMID 38345559, 2024). "CSMD3 encodes CUB and Sushi multiple domains 3, a tumor suppressor." (PMID 34616428, 2021). "Notably, in almost all cell lines (except for Huh7 and HepY2), miR-873 activation led to enhanced cell proliferation, consistent with the view that its target, CSMD3, was a tumor suppressor gene." (PMID 27918551, 2016).
tumor (continued). "Interestingly, we observed an increase in mesenchymal signature genes, such as the adhesion molecule CD44, the PDGF receptor beta, or PPRX, and an increase in the BRCA tumor suppressor and a decrease in some classical progenitor markers, such as prominin-1 or CSMD3." (PMID 36675105, 2023). "Seven of the 64 tumour suppressors (ACVR2A, CSMD3, EPS15, MAP2K4, NF1, PBRM1 and RB1) had intronic mis-splicing mutations in multiple tissues." (PMID 33420369, 2021). "Additionally, CRISPR/Cas9‐mediated knockout of CSMD3 inhibits the death of PDX tumour cells, which also suggests that CSMD3 is an important tumour suppressor." (PMID 35735060, 2022). "Besides, the humoral immune response was found in the mutually exclusive events (CSMD3 subtype two and EGFR subtype two), which was useful for autoimmunogenic human tumor antigens and cancers." (PMID 34076361, 2021). "We observed genetic heterogeneity also in spheroids for several genes, as indicated by low SNV frequencies, for instance, in ADAMTS7, CSMD3, ERN1, FAT3, and RAD51C/D, supporting the view that tumor lesions are composed of mixed tumor cell populations with varying frequencies of SNVs." (PMID 32533757, 2020).
cancer (52 papers, 2014 to 2025). A tumor composed of atypical neoplastic, often pleomorphic cells that invade other tissues. "The relatively high incidence of CSMD3 mutation in both human and canine UC, and the correlation with outcome in other human cancers, renders this gene a worthy candidate for an association with UC pathogenesis." (PMID 37079639, 2023). "Because CSMD3 had been implicated as a cancer-related gene in previous reports, we selected this gene for further study." (PMID 27918551, 2016). "Finally, we report the finding of CSMD3 mutation in 2 carcinomas." (PMID 39235515, 2025). "We observed other frequently-mutated genes in AS-HN including CSMD3, MUC16, and LRP1B, which are known cancer-related genes." (PMID 37106027, 2023). "CSMD3 mutation and TME are rarely discussed by researchers, despite the fact that it is one of the most commonly mutated genes in cancers." (PMID 36543836, 2022). "This duplication also recurrently affected known cancer census genes such as CSMD3, COX6C, EXT1, FAM135B, MYC, and NDRG1 in SG1 and SG3 in more than 75% of patients." (PMID 36129940, 2022). "Herein, we found 14 genes with UTR variants, of which four cancer-associated genes harbor variants in 3′ UTR (KDR and CARD11) and 5′ UTR (CSMD3 and TLX3)." (PMID 35884575, 2022). "As a result, 14 genes were found to be regulated by miRNAs (miRabel score ≤ 0.05), four of which are cancer-associated genes (CARD11, CSMD3, KDR, and TLX3)." (PMID 35884575, 2022). "Other cancer genes frequently altered in LC according to cBioPortal (e.g., ZFHX4, RYR2, CSMD3, FAT3, and RP1L1) were also found mutated at a high frequency in our cohort." (PMID 30925779, 2019). "The results showed that six cRMGs including OBSCN, CDKN2A, CSMD3, DMD, DNAH5, and KMT2Cwith MS or NS mutations have significant associations with prognosis in several cancer types." (PMID 30107644, 2018). "According to the Cancer Atlas of the Human Protein, CSMD3 are expressed in low to medium levels in the cytoplasm/membrane of 20 different cancer tissues." (PMID 27918551, 2016).
cancer (continued). "The remaining most frequent mutated cancer driver genes found in early-stage samples (KMT2C, ALK, BRCA2, GRM, ATM, and BRCA1) were not among those found to be the most frequently shared in late-stage samples (MUC16, CSMD3, KNT2C, NF1, LRP1B, SPEN, and TRRAP)." (PMID 37446001, 2023). "The CSMD3 gene has been investigated for its possible role in cancer progression." (PMID 36139405, 2022). "Interestingly, many novel cancer-associated genes identified by the excess of missense mutations are large genes with repetitive functional domains: LRP1B, CSMD3, FLG, USH2A and others." (PMID 30453881, 2018). "Additionally, four cancer-associated genes (CARD11, CSMD3, KDR, and TLX3) carried untranslated regions (UTRs) variants, which may impact gene regulation by affecting the miRNAs hybridization regions." (PMID 35884575, 2022). "Genes PTEN, CSMD3, and MUC16 also occur in more than half the cancer types, suggesting their relevance as general cancer driver genes that impact multiple cancer types." (PMID 39040139, 2024). "Gain in 8q chromosomal arm and especially in 8q24 region harboring amplifications in CSMD3, MYC and ASAP1 genes, has been described in different type of cancers." (PMID 36357817, 2023). "Based on host genome integration frequencies, we found previously reported integration sites in cancer for genes like FHIT, CSMD1, and LRP1B and putatively many new ones such as those exemplified in CSMD3, ROBO2, and SETD3." (PMID 33810183, 2021). "TCI indicated that CSMD3 and ZFHX4 are 4th and 12th most frequent SGA-FIs, and yet, they are designated as cancer drivers in previous studies." (PMID 31276486, 2019). "We identified two cancer cell lines, HGC27 and PC3, with CSMD3 and ZFHX4 amplification respectively, and we knocked down the expression of the two genes using siRNAs, followed by monitoring cellular phenotypes." (PMID 31276486, 2019). "Among Cancer Gene Census genes, 1346 events were detected in 947 different loci, with the most recurrent ones being those in CLTCL1 (24 cases), CSMD3 (21 cases), MYH9 (20 cases), ANK1 (19 cases), TPR (19 cases), MYH11 (18 cases), PTPN13 (18 cases), and POLQ (17 cases)." (PMID 33809641, 2021). "Interestingly, TCI revealed functional impact of certain SGAs with very high alteration frequencies, such as TTN, CSMD3, MUC16, RYR2, LRP1B, and ZFHX4, whose roles in cancer development remain controversial." (PMID 31276486, 2019). "CSMD3 and BCLAF1 are among the general cancer genes and SCLC-related genes." (PMID 29050228, 2017). "The top 15 SGA-FIs connected with CSMD3 and ZFHX4 also form densely connected networks that include well-known cancer drivers, such as KRAS, GATA3, KEAP1, ERBB2 and STK11, suggesting that alteration of CSMD3 and ZFHX4 may perturb some of the same signaling pathways as do these known drivers." (PMID 31276486, 2019). "Mutations in both CSMD3 and COL11A1 are not specific to any one cancer type, and these genes may be accruing mutations due to their long length." (PMID 29141020, 2017).
neurodevelopmental disorder (3 papers, 2013 to 2023). A behavioral and cognitive disorder with onset during the developmental period that involves impaired or aberrant development of intellectual, motor, or social functions. "Specifically, CSMD3 has been linked to synaptogenesis and neurogenesis in the context of neurodevelopmental disorders." (PMID 37761892, 2023).
CSMD3 also shares sentences with these, for which no sentence is quoted: gastric cancer (2 papers); adenocarcinoma (1); B-cell lymphomas (1); basal cell carcinoma (1); behavioral disorders (1); benign adult familial myoclonic epilepsy (1); cervical cancer (1); clear cell carcinoma (1); colorectal adenoma (1); dementia (1); epilepsy (1); familial colorectal cancer (1); follicular lymphoma (1); glioblastoma (1); gynecological cancer (1); lateral sclerosis (1); liver cancer (1); liver cirrhosis (1); liver diseases (1); liver fibrosis (1); neuroendocrine carcinoma (1); neuroendocrine tumors (1); ovarian serous cystadenocarcinoma (1); polycystic liver disease (1); prion disease (1); prostate adenocarcinoma (1); schizophrenia (1); staphylococcus aureus infection (1).